FBXL12 (F-box and leucine rich repeat protein 12)
Description:
Substrate-recognition component of the SCF (SKP1-CUL1-F-box protein)-type E3 ubiquitin ligase complex. Mediates the polyubiquitination and proteasomal degradation of CAMK1 leading to disruption of cyclin D1/CDK4 complex assembly which results in G1 cell cycle arrest in lung epithelia.
Synonyms: FBL12; FLJ20188
Tractability: PROTAC: ubiquitination databases record sites on it.
Gene: Protein-coding gene on chromosome 19 (9,810,267 to 9,827,816, reverse strand). Ensembl gene ENSG00000127452.
Subcellular location (Human Protein Atlas): Mitochondria
Pathways (Reactome):
Immune System: Antigen processing: Ubiquitination & Proteasome degradation
Metabolism of proteins: Neddylation
Gene Ontology:
Molecular function: protein binding
Biological process: regulation of cell cycle; SCF-dependent proteasomal ubiquitin-dependent protein catabolic process; protein ubiquitination
Cellular component: cytosol; cytoplasm; ubiquitin ligase complex
Genetic constraint (gnomAD): Loss-of-function variants: 24 observed, 24.12 expected, observed/expected ratio (o/e) 1, 90% interval 0.72 to 1.4. The upper end of that interval is the gene's LOEUF score, 1.4, which puts it in group 5 of 6, group 1 being the genes least tolerant of losing a copy. Missense variants: 384 observed, 416.28 expected, observed/expected ratio (o/e) 0.92, 90% interval 0.85 to 1. Synonymous variants: 193 observed, 186.57 expected, observed/expected ratio (o/e) 1.03, 90% interval 0.92 to 1.17.
Homologues: Orthologues: chimpanzee FBXL12 (100% identical), macaque FBXL12 (99% identical), dog FBXL12 (96% identical), pig FBXL12 (96% identical), mouse Fbxl12 (93% identical), rat Fbxl12 (93% identical), guinea pig FBXL12 (87% identical), rabbit FBXL12 (78% identical), tropical clawed frog fbxl12 (36% identical).
Diseases named in the same sentence as FBXL12 in open-access papers:
FBXL12 is named in the same sentence as 4 diseases in open-access papers, as found by Europe PMC text mining. Sharing a sentence is not in itself a finding about the gene and the disease. The quoted sentences say what the papers report.
cancer (1 paper, 2017). A tumor composed of atypical neoplastic, often pleomorphic cells that invade other tissues. "We detected insertion at the intronic region of RBM4 (chr11), known to be associated with cancer and ncRNA SMG1P5 (chr16), downstream of TINAGL1 (chr1) and LOC339807 (chr2) and at an intergenic region that is 30Kb upstream of ZNF846 and 11Kb downstream of FBXL12 in chromosome 19." (PMID 28410234, 2017).
tumor (1 paper, 2022). "For the cirReNET we built, there were many targeted genes involved in the mechanism of tumor genesis, such as AKT1, ErbB2, ITGB7, BAX, MAPK, FBXL12, CCL7 and so on." (PMID 35611168, 2022).
FBXL12 also shares sentences with these, for which no sentence is quoted: infection (1 paper); ischemic stroke (1).